SRXN1 (sulfiredoxin 1)
Description:
Contributes to oxidative stress resistance by reducing cysteine-sulfinic acid formed under exposure to oxidants in the peroxiredoxins PRDX1, PRDX2, PRDX3 and PRDX4. Does not act on PRDX5 or PRDX6. May catalyze the reduction in a multi-step process by acting both as a specific phosphotransferase and a thioltransferase.
Synonyms: C20orf139; SRX; SRX1; Npn3; YKL086W; dJ850E9.2
Tractability: Small molecule: a structure with a bound ligand is known. PROTAC: its protein half-life has been measured.
Gene: Protein-coding gene on chromosome 20 (646,615 to 653,378, reverse strand). Ensembl gene ENSG00000271303.
Subcellular location: Cytoplasm
Pathways (Reactome):
Cellular responses to stimuli: NFE2L2 regulating anti-oxidant/detoxification enzymes
Gene Ontology:
Molecular function: oxidoreductase activity, acting on a sulfur group of donors; protein binding; sulfiredoxin activity
Biological process: response to oxidative stress; cellular response to oxidative stress; cellular oxidant detoxification
Cellular component: cytoplasm; cytosol; endoplasmic reticulum membrane
Genetic constraint (gnomAD): Loss-of-function variants: 11 observed, 9.69 expected, observed/expected ratio (o/e) 1.14, 90% interval 0.71 to 1.78. That is too few expected variants to judge how well the gene tolerates losing a copy. Missense variants: 211 observed, 155.61 expected, observed/expected ratio (o/e) 1.36, 90% interval 1.21 to 1.52. Synonymous variants: 106 observed, 68.97 expected, observed/expected ratio (o/e) 1.54, 90% interval 1.31 to 1.8.
Homologues: Orthologues: chimpanzee SRXN1 (99% identical), rabbit SRXN1 (97% identical), dog SRXN1 (96% identical), macaque SRXN1 (96% identical), guinea pig SRXN1 (95% identical), pig SRXN1 (94% identical), mouse Srxn1 (90% identical), rat Srxn1 (75% identical), tropical clawed frog SRXN1 (61% identical), zebrafish srxn1 (52% identical), Drosophila melanogaster Srx (48% identical).
Diseases named in the same sentence as SRXN1 in open-access papers:
SRXN1 is named in the same sentence as 57 diseases in open-access papers, as found by Europe PMC text mining. Sharing a sentence is not in itself a finding about the gene and the disease. The quoted sentences say what the papers report.
lung carcinoma (10 papers, 2012 to 2025). "Studies have shown that SRXN1 is overexpressed in a variety of malignant tumours, including breast cancer, colorectal cancer, lung cancer, prostate cancer, and skin cancer." (PMID 37726767, 2023). "The SRXN1 (Sulfiredoxin 1), another phosphodiesterase 4D anchoring protein, was found to be upregulated in the lung cancer cell lines A549 and 95D and 75 NSCLC tissues compared with the adjacent non-tumor tissue." (PMID 36552904, 2022). "Studies had shown that SRXN1 was overexpressed in multiple types of malignancies, including cervical cancer, colorectal cancer, skin cancer, lung cancer, and renal cell carcinoma." (PMID 32955798, 2020). "Recent mounting evidence demonstrated that the overexpression of SRXN1 promoted the migration and invasion of multiple types of cancer cells, including cervical cancer, colorectal cancer cell, lung cancer, and melanoma." (PMID 32955798, 2020). "Nancy H. Colburna's group reported that SRXN1 promotes progression of lung cancer by modulating phosphokinase signalling." (PMID 32746503, 2020). "More importantly, both SRXN1 and KRT6A expression were significantly correlated with smoking so that we proposed an assumption that SRXN1 and KRT6A might be the key for preventing smoke cause lung cancer." (PMID 35071014, 2021). "We believed that SRXN1 and KRT6A might be the early diagnostic biomarkers and therapy targets on clinical therapy of smoke cause lung cancer with further validated study in future." (PMID 35071014, 2021). "Furthermore, higher SRXN1 expression levels were observed in squamous patients than in adenocarcinoma patients (P < 0.05), suggesting that SRXN1 might be correlated with the lung cancer subtype." (PMID 35071014, 2021). "Quantitative PCR and western blotting confirmed increased expression of Srxn1 and KRT6A mRNA and protein in lung cancer cell lines and non‐small cell lung cancer tissues." (PMID 40111164, 2025). "Because SRXN1 and KRT6A expression was upregulated in lung cancers, we designed three siRNAs to suppress the endogenous expression of SRXN1 and KRT6A transcripts." (PMID 35071014, 2021). "Quantitative PCR and western blotting validated the increased expression of SRXN1 and KRT6A mRNA and protein, respectively, in lung cancer cell lines and NSCLC tissues." (PMID 35071014, 2021). "A study found that knocking down TXNDC5 along with SRXN1 reduced the time needed for splicing XBP1 and spliced XBP1, resulting in the decreased expression of HSPA5, and among the handful of proteins that interact with SRXN1, PRDX6, PDIA6, and TXNDC5 were identified in lung cancer." (PMID 38666927, 2024). "In summary, these results suggest that SRXN1 and KRT6A might be potential biomarkers of smoking exposure and early lung cancer diagnosis and prognosis." (PMID 35071014, 2021). "Furthermore, we observed increased expression of SRXN1 and KRT6A mRNA and protein in lung cancer cell lines (95D, A549) and BEAS-2B-NNK cells, compared with normal BEAS-2B cells (both P < 0.05)." (PMID 35071014, 2021). "Notably, we identified SRXN1 and KRT6A as pivotal smoking-related genes (SRGs) with important roles in lung cancer carcinogenesis through subsequent experimental validation in vitro and in vivo." (PMID 35071014, 2021). "Furthermore, inhibition of SRXN1 or KRT6A suppressed viability and enhanced apoptosis in the A549 human lung carcinoma cell line." (PMID 35071014, 2021). "These previous studies confirm the important roles of SRXN1 and KRT6A in lung cancer." (PMID 35071014, 2021). "In summary, SRXN1 and KRT6A act as oncogenes in NSCLC and might be potential biomarkers of smoking exposure and the early diagnosis and prognosis of NSCLC in smokers, which is vital for lung cancer therapy." (PMID 35071014, 2021).
hepatocellular carcinoma (7 papers, 2020 to 2025). A malignant tumor that arises from hepatocytes. "Another study has also identified SRXN1 as pro-tumorigenic in hepatocellular carcinoma (HCC) by influencing ROS signaling." (PMID 41333220, 2025). "Recent studies have identified SRXN1 as a critical regulator of hepatocellular carcinoma (HCC) progression by neutralizing intracellular ROS and favoring cancer cell survival." (PMID 41131335, 2025). "In this work, we evaluated the prognostic power of SRXN1 for hepatocellular carcinoma using clinical specimens from both the public databases and Zhongshan Hospital." (PMID 32955798, 2020). "Srxn1 was found to be upregulated in samples of hepatocellular carcinoma." (PMID 40111164, 2025). "Differential expression of SRXN1 was verified in hepatocellular carcinoma and normal liver cells." (PMID 38244584, 2024). "SRXN1 enhances hepatocellular carcinoma progression by modulating lysosome biogenesis and autophagic flux, with its inhibition showing synergistic antitumor effects with sorafenib by increasing ROS levels, positioning it as a potential therapeutic target for HCC." (PMID 39315094, 2024). "However, the role of SRXN1 in hepatocellular carcinoma (HCC) is far from clear." (PMID 32746503, 2020).
cervical cancer (5 papers, 2017 to 2021). A primary or metastatic malignant neoplasm involving the cervix. "It has been reported that SRXN1 promotes metastasis of cervical cancer by regulating the Wnt/β‐catenin signalling pathway." (PMID 32746503, 2020). "The abnormal elevation of sulfiredoxin (Srx/SRXN1)—an antioxidant enzyme whose main function is to protect against oxidative stress—has been shown to be closely correlated with the progression of several types of cancer, including human cervical cancer." (PMID 28448437, 2017). "Moreover, it has been reported that SRXN1 promotes cell invasion, migration in cervical cancer via activating the Wnt/β-catenin signaling pathway, and could be a promising tool for the development of better therapeutic strategies for cancer prevention and treatment." (PMID 32327612, 2020).
acute pancreatitis (4 papers, 2021 to 2025). An acute inflammatory process that leads to necrosis of the pancreatic parenchyma. "For example, Srxn1 expression was upregulated in mild acute pancreatitis but decreased in severe cases." (PMID 40111164, 2025). "Furthermore, previous studies have found that inhibiting Srxn1 increased ROS and inflammatory responses in mice with acute pancreatitis, while overexpression of Srxn1 in acinar cells produced the opposite effect." (PMID 40111164, 2025). "Another study revealed that ROS and ER stress are attenuated by SRXN1 in acute pancreatitis." (PMID 39191723, 2024).
breast carcinoma (4 papers, 2020 to 2023). "Sulfiredoxin (SRXN1) was previously found to be associated with cerebrovascular disease in a Finnish cohort, and SRXN1 genetic polymorphisms were associated with breast cancer risk and survival." (PMID 36977240, 2023). "Polymorphisms in the SRXN1 gene have been shown to promote breast cancer development and influence patient survival." (PMID 32411320, 2020). "Besides, SRXN1 expression is associated with survival outcome in breast cancer." (PMID 32746503, 2020).
Cerebral ischemia (3 papers, 2015 to 2022). Restriction of arterial blood supply to the brain associated with insufficient oxygenation to support the metabolic requirements of the tissue. "Sulfiredoxin 1 (Srxn1), an endogenous antioxidant protein, plays an important neuroprotective role in cerebral ischemia." (PMID 25955519, 2015). "Rat corital astrocytes were exposed to OGD and H2O2 in order to mimic oxidative stress-induced injury in cerebral ischemia and used shRNAs to knockdown Srxn1." (PMID 25955519, 2015). "Srxn1 (Sulfiredoxin1), an endogenous antioxidant protein, could prevent cell oxidative stress and has been reported as up-regulation in cerebral ischemia/reperfusion (I/R) injury with neuroprotective effects." (PMID 36323676, 2022). "Srxn1 may be a potential target in the treatment of cerebral ischemia." (PMID 34457033, 2021). "Nevertheless, the specific function and related regulatory mechanisms of action of Srxn1 in cerebral ischemia and in damage induced by apoptosis have not been extensively investigated." (PMID 25955519, 2015). "However, the exact mechanisms of action of Srxn1 in cerebral ischemia have not yet been fully elucidated." (PMID 25955519, 2015).
skin cancer (3 papers, 2020 to 2023). "The over-expression of SRXN1 has been found in various cancers, including breast, colorectal, lung, prostate and skin cancers, and down-regulation has been found in esophageal cancer." (PMID 32455559, 2020).
colitis (2 papers, 2024). Inflammation of the colon. "Meanwhile, broccoli sprouts and bok choy increased the expression of antioxidants such as Nrf2, NADH-Quinone oxidoreductase 1, Gstm1, Srxn1, and GPx2 to improve colitis symptoms." (PMID 38779039, 2024).
gastric cancer (2 papers, 2020 to 2024). A primary or metastatic malignant neoplasm involving the stomach. "In addition, SRXN1 expression is increased in different human skin malignancies and gastric cancer." (PMID 32411320, 2020). "By integrating the final data, SOD2, sulfiredoxin 1 (SRXN1), neurogenic locus notch homolog protein 1 (NOTCH1), and mitogen-activated protein kinase 14 (MAPK14) were predicted to be the target genes for the anti-gastric cancer effects of WNG." (PMID 39252074, 2024).
liver diseases (2 papers, 2024 to 2025). "This Review explores SRXN1’s role in liver diseases, highlighting its protective effects on hepatocytes under pathological conditions such as acute liver injury, alcoholic liver disease and liver fibrosis." (PMID 41131335, 2025). "This Review aims to provide a comprehensive overview of SRXN1-mediated redox regulation of Cys oxidation, with a particular focus on its implications in liver disease mechanisms." (PMID 41131335, 2025). "We will explore the molecular mechanisms by which SRXN1 modulates redox signaling and discuss how dysregulation of this pathway contributes to the pathogenesis of liver diseases." (PMID 41131335, 2025). "Here we highlight the significance of SRXN1 in regulating Cys sulfinylation across a broad spectrum of liver diseases." (PMID 41131335, 2025). "A deeper understanding of SRXN1-mediated redox regulation may offer a novel therapeutic avenue to mitigate Cys oxidation and improve clinical outcomes in various liver disease contexts." (PMID 41131335, 2025). "Furthermore, the lack of longitudinal studies impedes a comprehensive understanding of how SRXN1 modulates disease trajectories or therapeutic responsiveness over time, particularly across different stages of liver disease." (PMID 41131335, 2025).
lung adenocarcinoma (2 papers, 2020 to 2021). A carcinoma that arises from the lung and is characterized by the presence of malignant glandular epithelial cells. "Research had suggested SRXN1 inhibitor might cause the death of human lung adenocarcinoma cells by increasing the level of ROS." (PMID 32955798, 2020).
melanoma (2 papers, 2020 to 2022). A malignant, usually aggressive tumor composed of atypical, neoplastic melanocytes. "SRXN1, on the other hand, appears to have a clearer role in promoting melanoma initiation; however, its exact role in melanoma progression and metastasis still needs to be elucidated." (PMID 35326683, 2022). "PRDXs 1-6 and SRXN1 have been reported to have elevated expression in melanomas and other cancers." (PMID 35326683, 2022).
non-small cell lung carcinoma (2 papers, 2020 to 2021). A group of at least three distinct histological types of lung cancer, including non-small cell squamous cell carcinoma, adenocarcinoma, and large cell carcinoma. "Non-parametric assessment of the correlations between clinicopathological factors and SRXN1 and KRT6A expression levels in 75 patients with non-small-cell lung cancer." (PMID 35071014, 2021).
Parkinson disease (2 papers, 2015 to 2016). A progressive degenerative disorder of the central nervous system characterized by loss of dopamine producing neurons in the substantia nigra and the presence of Lewy bodies in the substantia nigra and locus coeruleus. "It has been demonstrated that Srxn1 protects brain tissue from damage through the regulation of glutathionylation/deglutathionylation in Parkinson’s disease (PD)." (PMID 25955519, 2015).
preeclampsia (2 papers, 2022 to 2025). Preeclampsia is a hypertensive disorder of pregnancy that is characterized by new-onset hypertension with proteinuria presenting after 20 weeks of gestation, and depending on mild or severe forms may initially present with severe headache, visual disturbances, and hyperreflexia. "While typically associated with cancer pathways, SRXN1 was found to be markedly downregulated in a murine model of preeclampsia, correlating with impaired trophoblast viability, invasion, and myometrial migration—features mediated through ferroptotic mechanisms." (PMID 41020807, 2025). "Sulfiredoxin-1 (SRXN1), known for its antioxidant function, has also emerged as a candidate regulator of ferroptosis in preeclampsia." (PMID 41020807, 2025). "Immunohistochemistry analysis of placenta tissues showed that the NQO1 expression decreased in preeclampsia, whereas SRXN1 expression increased." (PMID 36061193, 2022). "Meanwhile, SRXN1 expression levels were significantly increased in preeclampsia placentas compared with normal control placentas (p < 0.05)." (PMID 36061193, 2022). "In our study, we confirmed that SRXN1 was elevated in human preeclampsia placentas." (PMID 36061193, 2022). "Regarding the potential of markers for discriminating preeclampsia patients from normal pregnant women, the ROC analysis revealed that the AUC values of the NQO1, SRXN1, CDO1, EGFR, FBXW7, and JUN are 0.803, 0.748, 0.708, 0.703, 0.665, and 0.681, respectively." (PMID 36061193, 2022).
prostate carcinoma (2 papers, 2023). A carcinoma that arises from epithelial cells of the prostate gland. "In this study, we found that SRXN1, as an antioxidative stress gene, plays an important role in radiotherapy for prostate cancer treatment, and this gene is also a potential biomarker for predicting the prognosis of patients treated with radiotherapy." (PMID 37726767, 2023). "Therefore, studying the association of SRXN1 expression with the GSVA score of the oxidative stress response may provide insights into the mechanism by which SRXN1 regulates the oxidative stress response in prostate cancer patients after radiotherapy." (PMID 37726767, 2023). "The up regulation of the ferroptosis biomarker gene SRXN1 confirms the role of Dt in making prostate cancer cells (particularly DU145 cells) more sensitive to ferroptosis." (PMID 36829917, 2023). "According to the analysis of prostate cancer cells, eight genes related to radiotherapy resistance were screened, and SRXN1 was identified as a potential biomarker for predicting the prognosis of prostate cancer in patients treated with radiotherapy." (PMID 37726767, 2023). "However, in prostate cancer, upregulation of the antioxidative stress factor SRXN1 leads to radiotherapy tolerance, which can potentially be used to predict the prognosis of prostate cancer patients after radiotherapy." (PMID 37726767, 2023). "This shows that prostate cancer patients with high expression of SRXN1 are not suitable for radiotherapy." (PMID 37726767, 2023). "We speculate that the high expression of SRXN1 will produce oxidative stress resistance in prostate cancer cells and thus inhibit cancer cell apoptosis, which is not conducive to the survival of radiotherapy patients." (PMID 37726767, 2023).
acute myeloid leukemia (1 paper, 2015). Acute myeloid leukemia (AML) is a group of neoplasms arising from precursor cells committed to the myeloid cell-line differentiation. "For example, SRXN1 (Sulfiredoxin-1), which is upregulated in all three SASP-treated PEL cell lines is involved in proliferation inhibition of acute myeloid leukemia mediated by Maesopsin 4-O-beta-D-glucoside, a natural compound isolated from the leaves of Artocarpus tonkinensis)." (PMID 25860939, 2015).
breast tumors (1 paper, 2024). "Pair-wise mRNA expression correlation analysis in human breast tumors from TCGA cohort showed a positive correlation between ZMYND8 and antioxidant genes including NQO1, GPX2, GCLC, GCLM, TXNRD1, and SRXN1." (PMID 38488001, 2024).
cardiac hypertrophy (1 paper, 2025). "Unexpectedly, all these changes induced by TAC in cardiac hypertrophy and cardiac fibrosis were significantly reversed by Srxn1 overexpression." (PMID 40111164, 2025). "We found that upregulating Srxn1 could improve cardiac function, as well as reduce myocardial hypertrophy and fibrosis following HF." (PMID 40111164, 2025). "However, whether Srxn1 overexpression has an effect on TAC‐induced cardiac hypertrophy and cardiac fibrosis has not been clarified." (PMID 40111164, 2025).
Cirrhosis (1 paper, 2020). A chronic disorder of the liver in which liver tissue becomes scarred and is partially replaced by regenerative nodules and fibrotic tissue resulting in loss of liver function. "However, SRXN1 level was merely associated with age, cirrhosis, and HBsAg in the validation cohort, due to the small sample size." (PMID 32955798, 2020). "As a result, we constructed a prognostic nomogram integrating SRXN1 expression and other independent prognostic factor including cirrhosis, HBsAg, and TNM stage." (PMID 32955798, 2020).
epilepsy (1 paper, 2023). A brain disorder characterized by episodes of abnormally increased neuronal discharge resulting in transient episodes of sensory or motor neurological dysfunction, or psychic dysfunction. "Similarly, at this time point, the levels of HO-1 and Srxn1 were increasingly maintained, suggestive of antioxidant defense response to cells during epilepsy development." (PMID 36600279, 2023).